Y_RNA (Y RNA )
Gene: Miscellaneous RNA gene on chromosome X (72,284,945 to 72,285,045, reverse strand). Ensembl gene ENSG00000238926.
Homologues: Orthologues: chimpanzee Y_RNA (100% identical), macaque Y_RNA (98% identical), guinea pig Y_RNA (90% identical). Paralogues in human: RNY3 (91% identical), Y_RNA (90% identical), Y_RNA (89% identical), RNY3P1 (88% identical), Y_RNA (88% identical), Y_RNA (87% identical), Y_RNA (86% identical), RNY3P11 (85% identical), Y_RNA (85% identical), Y_RNA (84% identical), RNY3P14 (83% identical), Y_RNA (83% identical), and 95 more.